ICAM1 (intercellular adhesion molecule 1)
Diseases named in the same sentence as ICAM1 in open-access papers (continued):
Sharing a sentence is not in itself a finding about the gene and the disease.
atherosclerosis (continued). "Therefore, the K469E polymorphism of the ICAM‐1 gene may strongly influence the expression and biological activity of ICAM‐1 and have a potentially important role in the inflammation, atherosclerosis, and pathogenesis of ischemic stroke." (PMID 31157518, 2019). "VCAM1 but not ICAM1 has been implicated in the early pathogenesis of atherosclerotic plaques, via promotion of monocyte adhesion and accumulation on vessel walls susceptible to developing atherosclerosis." (PMID 30563576, 2018). "In addition, ICAM-1 is the major adhesion molecule in the development of atherosclerosis." (PMID 30524759, 2018). "We found that atherosclerosis progression was markedly attenuated in mice deleted for ShcA in endothelial cells, that macrophage content was reduced at the sites of lesions, and that adhesion molecules such as the intercellular adhesion molecule-1 (ICAM-1) were severely reduced." (PMID 29540796, 2018). "In addition, studies in 113 patients with chronic hemodialysis showed an increase in cardiovascular risk factors (such as atherosclerosis) and mortality, which may be related to low levels of plasma H2S, activation of PKCβII, and upregulation of VCAM-1/ICAM-1." (PMID 30298008, 2018). "It is now widely accepted that both the production of intercellular adhesion molecules (ICAM-1) and their shedding onto endothelial and leukocytic surfaces play a pivotal role in mediating the interaction between endothelial cells and blood constituents at the early stage of atherosclerosis." (PMID 28050227, 2016). "Blood ICAM-1 and E-selectin levels are associated with the established CVD risk factors such as smoking, waist-hip ratio, blood pressure, HDL and total cholesterol, and are related to the earliest stages of atherosclerosis in obese, hypertensive and children with diabetes." (PMID 26809065, 2016). "Furthermore, patients with carotid artery atherosclerosis have been found to exhibit enhanced circulating levels of soluble E-selectin and intracellular adhesion molecule 1 (ICAM-1), which may serve as molecular markers for atherosclerosis." (PMID 26622474, 2015). "The two genes encode cell adhesion molecules (CAMs), namely ICAM-1 and VCAM-1, that are expressed on the surface of activated endothelial cells in response to inflammatory stimuli and mediate the attachment of circulating leukocytes to the endothelium, an early step of atherosclerosis." (PMID 25575156, 2015). "IL-6 also induces ICAM-1 expression on endothelial cells and may play a role in development and progression of atherosclerosis; adhesion molecules such as ICAM-1 and VCAM-1 play a significant role in cell recruitment within the intima during atheroma formation." (PMID 25490200, 2014). "Antibodies directed against vascular proteins such as vascular adhesion molecule-1 (VCAM-1), intercellular adhesion molecule-1 (ICAM-1), or selectins could be used to address vascular-related diseases such as atherosclerosis and visualise the sites of thrombus formation." (PMID 24804257, 2014). "Atherosclerosis is considered to be chronic vascular inflammation, initiated by increases in the endothelial expression of leukocyte adhesion molecules, such as E-selectin, intercellular adhesion molecule-1 (ICAM-1) and vascular endothelial adhesion molecule-1 (VCAM-1)." (PMID 25251368, 2014). "The upregulation of intercellular adhesion molecule-1 (ICAM-1) on the endothelium of blood vessels in response to pro-inflammatory stimuli is of major importance for the regulation of local inflammation in cardiovascular diseases such as atherosclerosis, myocardial infarction and stroke." (PMID 22716048, 2012). "Elevated ICAM1 and VCAM1 levels are considered hallmarks of a pro-inflammatory endothelium and contribute to vascular remodeling and atherosclerosis." (PMID 41293173, 2025). "SGLT2 inhibitors inhibit atherosclerosis by normalizing the expression of inflammation-related genes such as TNF-α, IL-6, ICAM-1, MMP2, and MMP9." (PMID 40869372, 2025).
atherosclerosis (continued). "This study emphasizes the importance of pathways such as Nrf2, ICAM-1, and p38 MAPK/p16INK4A in the development of atherosclerosis." (PMID 41470139, 2025). "Increases SOD and GSH in serum in diseased mice.Suppresses the expression of IL-6, TNF-α, ICAM-1, VCAM-1 and NLRP3.Ameliorates atherosclerosis." (PMID 41300435, 2025). "TNFRSF11B was positively correlated with the expression of intercellular adhesion molecule 1 (ICAM1), and increased the infiltration of monocytes into subendothelial spaces to promote atherosclerosis." (PMID 38333413, 2024). "Arterial lesions from both experimental atherosclerosis models and humans show increased expression of inflammatory biomarkers, such as MCP-1, E-selectin, ICAM-1, and VCAM-1." (PMID 39457059, 2024). "They examined cellular adhesion molecules, soluble ICAM-1 and soluble-VCAM-1, which are biological markers that show the progression and consequences of endothelial inflammation and atherosclerosis." (PMID 38233818, 2024). "Along the same line, HIV-1 RNA 50–200 copies/mL showed higher levels of intercellular adhesion molecule 1 (ICAM-1), which is an early biomarker of atherosclerosis, compared with VS (adjusted arithmetic median rate, 1.26; 95% CI, 1.07–1.48), in a recent study." (PMID 38352153, 2024). "It significantly increases the expression of intercellular adhesion molecule 1 (ICAM-1) and vascular cell adhesion molecule 1 (VCAM-1), thereby accelerating the inflammatory response of atherosclerosis." (PMID 38791032, 2024). "This modulation enhances the expression of intercellular adhesion molecule-1 (ICAM-1), MCP-1, vascular cell adhesion molecule 1 (VCAM-1), and IL-6, potentially accelerating the progression of atherosclerosis." (PMID 39726601, 2024). "Very recently, atherosclerosis has emerged as a new considerable ICIs-mediated side effect in cancer patients through VCAM-1 and ICAM-1 overexpression in the luminal membrane of vascular endotheliocytes." (PMID 39457081, 2024). "Elevated levels of ICAM-1 and VCAM-1 contribute to the initiation and progression of atherosclerosis by promoting the infiltration of inflammatory cells into the vascular wall, thereby exacerbating the inflammatory response and plaque formation." (PMID 38915995, 2024). "It has been well known that ICAM-1 and VCAM-1 play roles in arresting immune cells and initiating TEM, which plays an essential step in the development of atherosclerosis." (PMID 37228610, 2023). "Taken together, IL-32θA94V attenuated monocyte-endothelial adhesion by suppressing the expression of ICAM-1 and VCAM-1, which are key factors in atherosclerosis, via integrin-mediated signaling in HUVECs." (PMID 37228610, 2023). "On the other hand, it promotes ROS release, increases ICAM-1 and VCAM-1 content, promotes monocyte migration and EC adhesion, and participates in the pathogenesis of atherosclerosis." (PMID 34981330, 2023). "As part of the Atherosclerosis Risk In Communities (ARIC) study, a possible use of the adhesion molecules ICAM-1 and E-selectin as biomarkers for CHD and atherosclerosis in the carotid arteries was demonstrated." (PMID 37566005, 2023). "Whilst both VCAM‐1 and ICAM‐1 are upregulated in atherosclerotic lesions, data indicates VCAM‐1 plays a predominant role in the initiation of atherosclerosis." (PMID 37457144, 2023). "The activated endothelial cells can increase the expression of soluble ICAM-1 and soluble VCAM-1, and these molecules can mediate leukocyte adhesion to the endothelium and activate atherosclerosis formation." (PMID 37144001, 2023). "For example, nilotinib upregulates pro-atherogenic adhesion-proteins (ICAM-1 and VCAM-1), which induces atherosclerosis on the cell surface." (PMID 36814340, 2023). "Diosgenin prevents the intracellular adhesion molecule (ICAM-1), vascular cell adhesion molecule (VCAM-1), and protein expression involved in the development of atherosclerosis." (PMID 37520342, 2023).
atherosclerosis (continued). "IS increased the expression of the adhesion molecules ICAM-1, VCAM-1, MCP-1, and e-selectin, all of which are involved in the pathophysiology of atherosclerosis." (PMID 35448889, 2022). "Endothelial dysfunction is identified as an early indicator of atherosclerosis and is characterized by the high expression of VCAM-1 and ICAM-1." (PMID 35845572, 2022). "To validate the effect of APT1 on the H-Ras downstream signaling pathways, we measured the expression of p-ERK and its downstream atherosclerosis-related factors, such as MMP-9, VCAM-1, and ICAM-1." (PMID 35455042, 2022). "CRP induces a significant increase in the expression of intercellular adhesion molecule-1 (ICAM-1) and vascular cell adhesion molecule-1 (VCAM-1), which accelerates the inflammatory response in atherosclerosis." (PMID 36418968, 2022). "In the development of atherosclerosis (AS), miR-491-5p overexpression alleviates ox-LDL-induced HUVEC injuries by suppressing ICAM1." (PMID 36009063, 2022). "Meantime, the expression of pro-inflammatory factors, including intercellular adhesion molecule-1 (ICAM-1), vascular cell adhesion molecule-1 (VCAM-1), and interleukin-6 (IL-6) were increased, which led to vascular endothelial injury and atherosclerosis." (PMID 35935626, 2022). "And the endothelial cell dysfunction markers E-selection, ICAM-1, and VCAM-1 showed an increasing trend in the normal group, the diabetic group, and the diabetic with atherosclerosis group, which was consistent with the trend of QKi-7 among all groups." (PMID 35711530, 2022). "Interacting with FOXO1, METTL14 acts directly on the promoter regions of ICAM-1 and VCAM-1 to upregulate their transcription, thereby mediating the inflammatory response of endothelial cells in atherosclerosis." (PMID 36482903, 2022). "Subsequently, genes related to the atherosclerosis indicators EDN1, PTGIS, AGT, NOS3, ICAM1, and VCAM1 were detected by qPCR." (PMID 36180828, 2022). "ACA treatment also reduced the expression of atherosclerosis-related proteins, including CD68, α-SMA, ICAM-1, and TNFα, in the plaque area." (PMID 35563730, 2022). "In the early stage of atherosclerosis, the expression of VCAM-1 and ICAM-1 is upregulated as the inflammatory response increases, and the increased expression of CAM promotes the accumulation of inflammatory leukocytes in the vascular endothelium." (PMID 35788200, 2022). "This resulted in an increase in intercellular adhesion molecule 1 (ICAM-1) and vascular cell adhesion molecule 1 (VCAM-1), leading to mononuclear/endothelial cell adhesion and atherosclerosis." (PMID 36536469, 2022). "Subclinical atherosclerosis, represented by abnormal levels of CIMT, ICAM-1 and Lp(a), were significantly predominant among NAFLD subjects." (PMID 34191823, 2021). "TKIs have been shown to promote atherosclerosis by inducing the expression of pro-atherogenic adhesion molecules (CAM) on endothelial cells, including ICAM-1 (CD54), VCAM-1 (CD106) and E-Selectin (CD62E)." (PMID 34950060, 2021). "An increase in YKL-40 levels activate endothelial cells to express vascular adhesion molecule-1 (VCAM-1) and intercellular adhesion molecule-1 (ICAM-1), further injuring the vascular endothelial cells, and promoting the development of atherosclerosis." (PMID 33679587, 2021). "ICAM-1 and VCAM-1 have been proposed as early biomarkers of changes in the artery wall and to play a major role in the development of atherosclerosis; therefore, both are considered preclinical markers of endothelial dysfunction." (PMID 32433661, 2020). "Many clinical investigators have measured the levels of soluble ICAM-1 and VCAM-1 as the potential biomarkers for endothelial dysfunction and early atherosclerosis." (PMID 32089647, 2020). "Enhanced ICAM-1 and VCAM-1 expression, thus endothelial activation involved in atherosclerosis, was reported after acute and chronic distribution of IS by Six and colleagues." (PMID 33456671, 2020).
atherosclerosis (continued). "Monocyte migration and adhesion to endothelial cells are crucial steps in the early stages of atherosclerosis development, in which ligand-receptor pairs such as MCP-1/CCR2, ICAM-1/Integrin αMβ2, and E-selectin/Integrin αMβ2 are crucially involved." (PMID 32793587, 2020). "The soluble forms of adhesion molecules, including ICAM-1, VCAM-1, and E-selectin, induce inflammatory activity in the dysfunctional endothelium in patients with atherosclerosis and diabetes." (PMID 32397494, 2020). "Genetic depletion of NEXN-AS1 dramatically increased atherosclerosis in ApoE–/– mice, with concurrent increases in markers of vascular inflammation such as VCAM-1, ICAM-1, TNF-α, and MCP-1." (PMID 33021969, 2020). "The ICAM‐1/LFA‐1 adhesion system regulates leukocyte interactions, migration and adhesion and appears to play an important role in early atherosclerosis." (PMID 31157518, 2019). "In the early phase of atherosclerosis, LPS, inflammatory cytokines, or oxidized LDL promotes the protein expression of adhesion molecules such as VCAM-1 and ICAM-1 and the secretion of monocyte chemoattractant protein 1 (MCP-1) in endothelial cells." (PMID 31248152, 2019). "The augmented response of MCP‐1, ICAM‐1 and VCAM‐1 to a given concentration of urate would stimulate downstream inflammation and thereby induce atherosclerosis progressing to a greater extent than controls in vitro." (PMID 30690853, 2019). "Recent studies also suggested that soluble adhesion molecules, including ICAM-1, E-selectin, VCAM-1, and P-selectin, play an important role in the pathogenesis of atherosclerosis." (PMID 31771561, 2019). "During the development of atherosclerosis, BMP4 produced in endothelial cells, which then leads to ICAM-1 induction and monocyte binding." (PMID 31064817, 2019). "In oscillatory shear stress (OSS)-induced atherosclerosis, CSE expression is down-regulated, and NaHS activates eNOS and decreases the expression of intercellular ICAM-1, thereby inhibiting OSS-promoting atherosclerosis." (PMID 30298008, 2018). "Furthermore, ICAM-1, a cell surface glycoprotein, is a member of theimmunoglobulin superfamily of adhesion molecules, responsible for the adhesion ofcirculating leukocytes to the activated endothelium, which is one of the firstevents in the pathogenesis of atherosclerosis." (PMID 29944163, 2018). "Like ECs, VSMCs also express intercellular adhesion molecule 1 (ICAM-1) and vascular cell adhesion molecule 1 (VCAM-1) in atherosclerosis, restenosis, and transplant vasculopathy." (PMID 30406116, 2018). "In particular, CXCR4, ICAM-1, Tumor Necrosis Factor Alpha-Induced Protein 3 (TNFAIP3), and Caspase-8 (CASP8) genes that present a role in atherosclerosis development at different level and with different functions were considered." (PMID 30356351, 2018). "In fact, ICAM-1 together with IL-6, IL8 play an important role in the progression of atherosclerosis through triggering the transendothelial migration of immune cells to the site of inflammation and the activation of pro-inflammatory cascades in target cells." (PMID 30131806, 2018). "This study was aimed to explore ICAM-1 and VCAM-1 expression of cardiac tissue from the early progression of atherosclerosis in dyslipidemia in Sprague Dawley rat model." (PMID 30505360, 2018). "Ox-LDL induces endothelial dysfunction and changes of intercellular adhesion molecule-1 (ICAM-1), vascular cell adhesion molecule-1 (VCAM-1), and E-selectin, which are involved in the pathogenesis of atherosclerosis." (PMID 30050659, 2018). "Focusing on the role of chemokines in early stages of atherosclerosis development, gene expressions of CXCR4 and ICAM-1 mediators were also analyzed." (PMID 30356351, 2018). "Adhesion molecules (ICAM-1 and VCAM-1) expressed by endothelial cells are involved in the recruitment and transendothelial migration of leucocytes leading to the initiation of atherosclerosis." (PMID 28399171, 2017).
atherosclerosis (continued). "The interaction of endothelial cells and monocytes in atherosclerosis is mediated through adhesion molecules, among which are VCAM-1 and ICAM-1." (PMID 28593025, 2017). "The authors selected E-selectin, P-selectin, VCAM-1, ICAM-1 and MCP-1 cytokines as endothelial dysfunction biomarkers related to the early stages of atherosclerosis." (PMID 28335517, 2017). "Herein, ICAM-1, VCAM-1, MCP-1, TNF-α, IL-1β, and MMPs-9, which participate in initial and later stages of atherosclerosis, will be more elaborately discussed." (PMID 29038791, 2017). "In order to further understand the potential mechanism of the inhibitory effect of naringin on anti-atherosclerosis, we analyzed the effect of naringin on the mRNA expression of VACM-1, ICAM-1, and E-selectin by real time PCR method and Western blot." (PMID 26861272, 2016). "Endothelial activation is the initial event of atherosclerosis development and is activated by expression of multiple cell adhesion molecules including VCAM-1, ICAM-1 and E-selectin." (PMID 27799085, 2016). "Expression of CAMs such as ICAM-1, VCAM-1, and E-selectin mediates proinflammatory state and leads to formation of atheroma resulting in atherosclerosis." (PMID 27366195, 2016). "The NF-κB transcriptional factor drives the expression of chemokines and adhesion molecules, such as ICAM-1 and VCAM-1, which recruit monocytes to diseased endothelium and initiates the development of atherosclerosis." (PMID 27249230, 2016). "Several cytokines (e.g. IL1β, IL6, and TNFα) are known to stimulate the expression of ICAM-1 and VCAM-1, two important molecules involved in the development of atherosclerosis." (PMID 27277003, 2016). "Some authors have suggested that ICAM-1 is predictive in initially healthy people and VCAM-1 in patients with atherosclerosis." (PMID 25784313, 2015). "Several studies have demonstrated that, in addition to endothelial cells, VSMCs also express ICAM-1 and VCAM-1 in atherosclerosis and vascular diseases." (PMID 25716870, 2015). "In this experimental model, expression of ET-1 and inducible adhesion molecules such as ICAM-1 and VCAM-1 in the arterial wall represented a key event in the development of atherosclerosis." (PMID 26504474, 2015). "Interleukin-6, TNF-α, VCAM1, ICAM1 and MCP-1 are important inflammatory cytokines that are engaged in the development of atherosclerosis, which can exacerbate it." (PMID 25661015, 2015). "VCAM-1 seems to have a more crucial role than ICAM-1 in mechanisms leading to increased LVMI, i.e. atherosclerosis and hypertension." (PMID 26398099, 2015). "The released NF-κB dimers enter the nucleus and activate the expression of many genes involved in the initiation and progression of atherosclerosis, including cytokines (e.g., TNF, IL-6), adhesion molecules (e.g., VCAM-1, ICAM-1) and chemokines (e.g., MCP-1)." (PMID 26322890, 2015). "Intercellular adhesion molecule-1 (ICAM-1), an important immune adhesion molecule, is related to the atherosclerosis." (PMID 25310099, 2014). "ICAM-1 and VCAM-1 were measured as markers of endothelial dysfunction; considered the earliest stage in the atherosclerosis process." (PMID 25115868, 2014). "In this experimental model, the expression of ET-1 and inducible adhesion molecules such as ICAM-1, VCAM-1, and E-selectin in the arterial wall represent a key event in the development of atherosclerosis." (PMID 24719637, 2014). "The NP-mediated vascular effects include expression of endothelial cell adhesion molecules such as intercellular adhesion molecule 1 (ICAM-1) and vascular cell adhesion molecule 1 (VCAM-1), vasomotor dysfunction and accelerated progression of atherosclerosis." (PMID 25184212, 2014). "One of the earliest important events during the initiation of atherosclerosis is the expression of adhesion molecules by vascular endothelial cells, including VCAM-1 and ICAM-1." (PMID 24722330, 2014).